CD22 (CD22 molecule)
Diseases named in the same sentence as CD22 in open-access papers (continued):
Sharing a sentence is not in itself a finding about the gene and the disease.
tumor (continued). "MT-SLP-76-overexpressing CD22 CAR T cells mediated sustained tumor eradication, whereas CD22 CAR T cells alone induced only modest tumor control." (PMID 41131392, 2025). "For B cells, CD20+, CD22+, ADAM28+, and BIRC5 have been identified within tumor‐associated TLSs and are implicated in enhancing the response to ICI therapy." (PMID 41235705, 2025). "Conversely, negative selection resulted in reduced cytokine levels in response to CD22+ B-ALL, but a quicker ex vivo tumor killing rate with significant enrichment of anti-CD22 CAR Vδ1 and Vδ2 T cells." (PMID 40148988, 2025). "Tumor biopsy after disease progression revealed strong positive CD22 and partial positive CD19 expression." (PMID 41235228, 2025). "It was previously shown that CD22 CAR T cells expand poorly in response to the CD22-low tumor cells in this model." (PMID 41131392, 2025). "A similar phenomenon has also been reported in acute lymphoblastic leukemia in which CD22 is trogocytosed to CAR-T cells from tumor cells leading to their destruction." (PMID 41181711, 2025). "Preclinical studies have highlighted the potential of 177Lu-labeled CD22-specific radioimmunoconjugates, showing potent anti-tumor activity in NHL models." (PMID 40227793, 2025). "The binding of InO to CD22-expressing tumor cells initiates endocytosis of the InO-CD22 complex, leading to hydrolysis of the N-acetyl-γ-khakimycin dimethylhydrazide junction." (PMID 38519953, 2024). "In practice, CLASH promotes the proliferative capacity and efficacy of CAR-T cell variants in blood and solid tumour models, which include the CD19 + CD22 + NALM6 tumour model and HER2 + HT29 tumour model." (PMID 39427211, 2024). "We observed that pretreatment of tumor cells with Rituximab enhanced the expansion of CD19/CD22 CAR-T cells in vitro." (PMID 38662336, 2024). "And in ligand-receptor interaction, the B cells activation group showed more active CSF, CXCL, and MHC-I signaling pathway, while CD22 was inhibited, indicating that the B cells activation group improved anti-tumor immunity through cell-cell interactions." (PMID 38622125, 2024). "Such strategies can potentially disrupt the protective signals that CD22 provides to tumor cells, thereby enhancing the efficacy of treatments aimed at eradicating B cell malignancies." (PMID 38881902, 2024). "The new immune cells showed significant binding affinity and cytotoxicity to CD22 + lymphoma cells and reduced tumor growth in tumor-bearing mice." (PMID 37587290, 2024). "Soluble CD22 is generated by the cleavage of the extracellular domain on the membrane surface and is a tumor marker for B-cell malignancies." (PMID 38711503, 2024). "Surprisingly, while T cells expressing ChTCRs using each scFv bound soluble CD22 protein, only T cells expressing the 9A8 ChTCR formed an organized immune synapse and recognized CD22 positive tumor cells." (PMID 38746248, 2024). "In the case of CD-22 positive tumor, the patient showed complete remission after the administration of CAR-T and maintenance of anti PD-1 and the patient had progression-free survival (PFS) of 35 months till the cutoff date." (PMID 38799440, 2024). "Weekly blood samples were also analyzed via flow cytometry to examine the number of circulating CD19+ tumor cells and CD22-CAR-T cells, with CAR-T cells expressing 1ug36-sdCAR showing the highest CAR-T expansion in vivo." (PMID 38596311, 2024). "Re-biopsy of enlarged pericolic lymph nodes confirmed refractory BL and indicated partial CD19 expression (in 50% of tumor cells) and uniform expression of CD22 (in 100% of tumor cells)." (PMID 39717765, 2024). "Modulated by genetic engineering techniques, macrophages can target specific antigens, such as CD19, CD22, and Her2, to identify tumor cells." (PMID 39042294, 2024). "Here we identify CD22, a well-known tumor surface marker in hematologic malignancies, is expressed in ESCC, possibly serving as a potential target of CAR-NK cell therapy." (PMID 37817249, 2023).
tumor (continued). "Other B-cell lineage markers, as CD20 and CD22, have also been targeted, and epigenetic modifying agents have also been tested to overcome the immune evasion of tumor cells during therapy with CAR T-cells." (PMID 37893067, 2023). "Several other CD22-targeted scFv structures have shown remarkable preclinical anti-tumor activity and have been adopted in clinical practice." (PMID 37821931, 2023). "An antibody-drug conjugate that is internalised by CD22+ tumour cells, delivering the conjugated anti-cancer antibiotic, N-acetyl-γ-calicheamicin, which induces double-stranded DNA breaks leading to cancer cell cycle arrest and apoptosis." (PMID 37681023, 2023). "As CD22 is always expressed in B cells, it should be noted that the expression of CD22 in lymphocytes within the tumor would be a good internal control for IHC staining quality." (PMID 37817249, 2023). "Taken together, these data show a significant anti-CD22 CAR control of different tumor models, with an advantage of m971-CAR over IS7-CAR." (PMID 37269947, 2023). "In a second patient, CD22 was expressed mostly in the cytoplasm of tumor cells, while in some cases, CD22-positive lymphocytes were found in the stroma." (PMID 37817249, 2023). "In our study, 25 patients (100.0%) with a high tumor burden achieved CR in the tandem CD19/CD22 group." (PMID 37095120, 2023). "Immunohistochemical (IHC) staining was performed on tumor specimens from 97 TNBC patients for CD22 expression." (PMID 36768478, 2023). "As an attractive target in hematological malignancies, we report here that CD22 is an ESCC tumor antigen." (PMID 37817249, 2023). "And the tumor cell proportion rate is up to more than 60% in the majority of CD22-positive ESCC samples which indicates that CD22 is widely expressed across tumor cells." (PMID 37817249, 2023). "And we found that the tumor cell proportion rate was up to more than 60% in the majority of CD22-positive ESCC samples which indicated that CD22 was widely expressed across tumor cells." (PMID 37817249, 2023). "In attempts to reduce tumor escape through antigen loss, simultaneous targeting of multiple antigens, such as a combination of CD19 and CD22, has also been considered." (PMID 37864230, 2023). "GSEA analysis indicated that CD22-mediated BCR modulation, cell cycle checkpoints, FCGR activation, and mitotic prometa centrally involve in regulating neoplasm development and immune response in high-risk individuals." (PMID 37059592, 2023). "As we have noted, a direct equimolar comparison of dosing between blina and 197 is challenging due to a number of factors, including differential internalization behavior and antigen density of CD19 and CD22 on target tumor cells." (PMID 37247022, 2023). "Co-administration of CD19 and CD22 CAR-T cells can kill CD19+CD22−, CD19−CD22+, and CD19+CD22+ tumor cells, thereby avoiding tumor escape caused by heterogeneous expression of antigens." (PMID 36949487, 2023). "VH-Fc 1-16-3 DDC and VH-Fc E1-2 DDC worked efficiently in combination (with equivalent input) in CD22 positive tumor cells (Raji and Bjab) as well (–G)." (PMID 35464476, 2022). "In one another encouraging published outcome, prescribing the blinatumomab, a BiTE, alongside anti-CD22 CAR-T cell led to the complete eradication of tumor cells and patients’ prolonged life span who relapsed after anti-CD22 CAR-T cell monotherapy." (PMID 36419058, 2022). "The most advanced radiolabelled anti-CD22 Ab is 90Y-epratuzumab, showing anti-tumor effects in both indolent and aggressive NHL in a phase I trial with mainly grade 3–4 hematological toxicities." (PMID 35865548, 2022). "We measured the expression levels of CD22 and PD‐L1 on different tumor cell lines (Raji, Daudi, BV173, and K562) using flow cytometry." (PMID 35665369, 2022). "VH-Fc E1-2 showed moderate killing of CD22 positive tumor cells, while VH-Fc 1-16-3 showed approximately 10-fold greater potency in comparison to VH-Fc E1-2." (PMID 35464476, 2022).
tumor (continued). "A reduction in CD22 surface expression was sufficient to drive tumor evasion from anti-CD22 CAR T-cells despite ongoing dim CD22 expression." (PMID 35199207, 2022). "Choice between these therapies depends on several factors, such as donor availability, the presence of CD19 + or CD22 + on blast cells, tumor burden, toxicity, previous therapies." (PMID 35950202, 2022). "Previous in vitro studies have demonstrated that dual CD19/CD22 CAR-NK cells have anti-tumor activity against the ALL cell line." (PMID 36612114, 2022). "A CD19/CD22 Loop Bi-CAR with membrane-proximal CD22 CAR was shown to be more effective than the Tandem Bi-CAR in eradicating tumor cells and prolonging survival in mouse models." (PMID 35805001, 2022). "The culture supernatant was harvested from tumor cells and was used to induce the expression of PD‐L1 on CD22 CAR‐T cells." (PMID 35665369, 2022). "Preclinical investigation of the CD22 CAR-T therapy against B-cell malignancies was evaluated by coculturing CD22 CAR-T cells with tumor cell lines or primary blasts from patients in vitro and using a xenograft mouse model in vivo." (PMID 35317863, 2022). "In vitro validation demonstrated strong activation and cytotoxicity of CD22 CAR-T cells by monitoring residual CD22+ tumor cell lines, detecting CD107a and cytokine release levels." (PMID 35317863, 2022). "PD‐L1 was significantly upregulated on CD22 CAR‐T cells when they were co‐incubated with tumor cells at different time points." (PMID 35665369, 2022). "Lastly, high levels of expression of certain tumor-associated antigens (TAAs; CD19, CD20, CD22, and CD38) in most B cell malignancies are correlated with a high proliferation rate and disease progression." (PMID 36551511, 2022). "The team of Hong S also reported a chemoenzymatic glycocalyx editing strategy to introduce high-affinity and specific CD22 ligands onto NK-92MI and cytokine-induced NK cells to achieve tumor-specific CD22 targeting." (PMID 36601109, 2022). "Pathway analysis comparing PL4–5 against PL1–3 in tumor samples indicated upregulation of cytokine and interleukin signaling and downregulation of CD22-mediated B-cell receptor (BCR) regulation in PL4–5." (PMID 34642171, 2022). "Out of the 140 DE genes, 73 code for different domains of immunoglobulins as well as B-cell receptors such as CD19 and CD22, showing important upregulation of the B-cell activity in the immune infiltrate of the tumor." (PMID 36012390, 2022). "The group of mice treated with Chidamide presented higher CD22 expression in tumor cells, consistent with the previous." (PMID 34667217, 2021). "The impressive anti-tumor function of CD22-CAR T cell was reported in relapsed cancer after CD19-CAR T cell therapy or in eradicating the ALL tumor cells." (PMID 34412685, 2021). "On the contrary, our analysis revealed an opposite trend of alterations for CDH1 and CD22 within the explored neoplasms." (PMID 34202213, 2021). "In a NOD/SCID/ɣ (NSG) mouse CD19+/CD22+ tumor model, AUTO3 demonstrated improved efficacy over the FMC63 CAR with equivalent persistence in the bone marrow." (PMID 34642489, 2021). "In the SW900 model, doses as low as 0.1 mg/kg of anti-Ly6Ev2-CBI enabled modest tumor regression, and the 0.2 mg/kg dose was substantially separated from the untargeted control (anti-CD22)." (PMID 33382956, 2021). "On day 13, the site density of CD22 on the surface of tumor cells in peripheral blood was measured and CAR T cells were injection at a dose of 1 × 107 cells." (PMID 34667217, 2021). "Functional assessment was performed of the CD19/22 and CD22 CAR T-cells using killing assays against the NALM6 tumor cell line and cytokine secretion analysis." (PMID 34819105, 2021). "One particular format targets the cytotoxic potential of immune effector cells (IECs) by bridging an activating receptor on IEC (e.g., CD3ε on T cells) and an antigen (e.g., CD22) on malignant cells for subsequent tumor cell lysis." (PMID 34827170, 2021).
tumor (continued). "CD22 was also expressed on the surface of primary tumor cells in 2 cases, and the positivity rate was also 100%." (PMID 34667217, 2021). "CARs that target other B-cell lineage antigens such as CD20 and CD22 have been incorporated in the hope of combatting both tumor heterogeneity as well as antigen escape with dual targeting CARs such as the anti-CD19/CD22 CAR." (PMID 33925571, 2021). "In vivo, this anti-CD22-NMS249 ADC was at least as effective as an anti-CD22-VC-MMAE ADC in xenograft tumor models but retained its effectiveness in a model based on cell lines resistant to the anti-CD22-VC-MMAE ADC." (PMID 32937862, 2020). "Briefly, patient 2 relapsed after cell therapy through an acquired tumor resistance mechanism (loss of CD19 and diminished expression of CD22 to a level below the threshold needed to elicit anti-tumor functions)." (PMID 32245502, 2020). "NK cells metabolically engineered to display a sialic acid derivative showed enhanced binding to CD22-positive tumor cells, resulting in tumor killing and therapeutic efficacy." (PMID 32764348, 2020). "Although the activity to the tumor was quite low, the increase over time of the cumulated activity confirmed the specificity of canine CD22 targeting in this mouse model." (PMID 32117707, 2020). "We found that T cells transduced with the CD19/CD22 CAR vector yielded strong induction of cytokines in the presence of tumor target that is similar in magnitude." (PMID 32245502, 2020). "The importance of surface receptors such as CD19 and CD22 to treat B-cell malignancies are obvious considering multiple successful constructs proved to perform sufficient tumor elimination." (PMID 29316610, 2018). "The proportion of tumor cells in the G2/M phase significantly increased in cells treated with DOX–platelet–CD22 compared with that in cells treated with DOX–platelet." (PMID 28938559, 2017). "Next the in vivo distribution of DOX–platelet–CD22 in tumor-bearing mice was characterized using optical imaging." (PMID 28938559, 2017). "In conclusion, the present study has introduced a novel fusion protein for specific targeting of CD22-positive tumor cells." (PMID 28582973, 2017). "CD22 has attracted particular attention as a chemoimmunoconjugate for targeted cytotoxic drug delivery to tumor cells because antibodies that are bound to CD22 can be rapidly internalized." (PMID 28938559, 2017). "The results of TdT-mediated dUTP nick end labeling (TUNEL) staining for tumor tissues also showed that apoptosis in tumor tissues from mice that were treated with DOX–platelet–CD22 obviously increased." (PMID 28938559, 2017). "In the KOPN-8 model, CD22-targeting rIT alone reduces tumor burden below the detection level by bioluminescence or flow cytometry and only a few cells remain, presumably responsible for late relapse and animal death." (PMID 28423727, 2017). "In summary, our proposed DOX–platelet–CD22 drug delivery system is biocompatible with normal tissues and specific to tumor cells." (PMID 28938559, 2017). "The results revealed that loading DOX on platelets conjugated with anti-CD22 mAbs greatly improved DOX accumulation in tumor tissues." (PMID 28938559, 2017). "All ADCs demonstrated statistically significant tumor efficacy compared to the anti-CD22 ADC (p<0.001) at all doses except for the anti-Her2 Cys-ADC at 1 mg/kg." (PMID 24454709, 2014). "After 48 hours of co-culture, growth of CD22+CD3− tumor cells were observed when mock transduced T cells were used as effector cells." (PMID 24358223, 2013). "Residual tumor cells were distinguished from T cells in the assays using antibodies against CD22 and CD3, respectively, as Ramos cells are CD22+." (PMID 24358223, 2013). "Giving 5 mg of SAP complexed with a pair (50 mg) of anti-CD22 BsAbs over 15 days provided a marked clinical response, including complete clearance of tumor from the blood, clearance of ascites and shrinkage of tumor masses." (PMID 22069735, 2011).
tumor (continued). "This may occur because CD19 combined with CD22 has more efficient tumor clearance and more precise T-cell functional activation." (PMID 40433368, 2025). "AuLtNps exhibited a proinflammatory cytokine secretion profile with increases in CD3, CD8+ T, and CD4+ T cells, as well as an increase in the proportion of CD22+ cells, suggesting that nanoparticles obtained using tumor lysate as a reducing agent activate both humoral and cellular immunity." (PMID 40143109, 2025). "Compelling new evidence also links trogocytosis to therapeutic resistance, particularly in chimeric antigen receptor (CAR-T and CAR-NK) cell therapies, where tumor antigens like CD19 and CD22 are siphoned off by effector cells, leading to T cell fratricide, functional exhaustion and tumor relapse." (PMID 41181711, 2025). "Collectively, these results suggested that LoopCAR-1 and LoopCAR-4 could achieve in vivo CD19+CD22+ tumor clearance activity comparable to that of the CD19 CAR." (PMID 38823002, 2025). "This is consistent with a previous report that low surface density of the target (CD22), rather than total loss of its expression on tumor cells, is sufficient to allow escape from CAR therapy." (PMID 39554906, 2024). "InO can bind to CD22‐expressing tumor cells, leading to internalization of the ADC‐CD22 complex." (PMID 39070179, 2024). "Additionally, when neutrophils are incubated with epratuzumab (anti-CD22)-opsonized Daudi B lymphoblast cells, there is a transfer of CD22 from tumor cells to neutrophils." (PMID 38474175, 2024). "In brief, it can be used in the delivery of CD22 CAR-NK towards tumor cells." (PMID 37817249, 2023). "In their next study, they confirmed that short interval sequential infusions of CD19/CD22/CD20 CAR-T cells could enhance expansion of prior CAR-T cells with stronger tumor-killing capacity." (PMID 38003910, 2023). "Through chi-square test, expression of CD22 in ESCC was associated with lymph node metastasis while it was no related to the depth of tumor invasion and clinical stage." (PMID 37817249, 2023). "Clinical data showed that CD22 density on the tumor cell surface correlated with clinical outcomes." (PMID 37821931, 2023). "Furthermore, we propose some perspectives for overcoming tumor escape and enhancing the efficacy of CD22-targeted therapies." (PMID 37821931, 2023). "In our study, high expression of CD22 in TNBC might also be negatively correlated with SHP-1, and CD22 might contribute to TNBC tumor progression." (PMID 36768478, 2023). "In summary, gut microbiota regulation by L_H and HK_H may affect CD22-mediated BCR regulatory processes in the tumor immune microenvironment to alleviate CRC progression in AOM/DSS mice." (PMID 37960165, 2023). "We noticed that tumor cells induced PD‐L1 expression on the surface of CD22 CAR‐T cells." (PMID 35665369, 2022). "For example, bryostatin has been shown to increase CD22 on tumor cells and has demonstrated safety in clinical trials and could therefore be given prior to CAR for patients with low CD22 expression to try to improve CAR efficacy." (PMID 35844298, 2022). "Future studies are necessary to investigate whether T cell‐expressed PD‐L1 affects the in vivo anti‐tumor activities of CD22 CAR‐T cells in primary cell or patient‐derived xenografts." (PMID 35665369, 2022). "To investigate whether tumor‐induced PD‐L1 affects the functions of CD22 CAR‐T cells, we further generated a CD22 CAR/PD‐1ED construct expressing the PD‐1 ED that can lead to engagement of CAR‐T cells through PD‐1‐PD‐L1 ligation." (PMID 35665369, 2022). "The results showed that the in vivo tumor cells did modulate CD22 expression in response to Chidamide and the effect of upregulation for CD22 expression was most significant at day 6 after the first gavage but could last for 9 days." (PMID 34667217, 2021). "In vitro and in vivo results showed that DOX–platelet–CD22 could target tumor tissues, which significantly decreased the tumor volume compared to the control groups." (PMID 34834304, 2021).